STAB2 (stabilin 2)
Description:
Phosphatidylserine receptor that enhances the engulfment of apoptotic cells. Hyaluronan receptor that binds to and mediates endocytosis of hyaluronic acid (HA). Also acts, in different species, as a primary systemic scavenger receptor for heparin (Hep), chondroitin sulfate (CS), dermatan sulfate (DS), nonglycosaminoglycan (GAG), acetylated low-density lipoprotein (AcLDL), pro-collagen propeptides and advanced glycation end products (AGE). May serve to maintain tissue integrity by supporting extracellular matrix turnover or it may contribute to maintaining fluidity of bodily liquids by resorption of hyaluronan. Counter receptor which plays an important role in lymphocyte recruitment in the hepatic vasculature. Binds to both Gram-positive and Gram-negative bacteria and may play a role in defense against bacterial infection. The proteolytically processed 190 kDa form also functions as an endocytosis receptor for heparin internalization as well as HA and CS.
Synonyms: FEEL-2; FEEL2; FELL; FEX2; HARE; DKFZP434E0321; STAB-2; SCARH1; FELE-2; FELL2
Tractability: Antibody: UniProt places it where antibodies can reach, with high confidence; its Gene Ontology location is reachable by antibodies, with high confidence; UniProt predicts a signal peptide or a membrane-spanning region.
Gene: Protein-coding gene on chromosome 12 (103,587,273 to 103,766,719, forward strand). Ensembl gene ENSG00000136011.
Subcellular location: Cell membrane; Cytoplasm
Subcellular location (Human Protein Atlas): Cytosol
Pathways (Reactome):
Metabolism: Hyaluronan degradation; Hyaluronan metabolism
Vesicle-mediated transport: Scavenging by Class H Receptors
Gene Ontology:
Molecular function: low-density lipoprotein particle binding; low-density lipoprotein particle receptor activity; protein binding; scavenger receptor activity; cargo receptor activity; hyaluronic acid binding; protein-disulfide reductase activity; calcium ion binding
Biological process: defense response to bacterium; defense response to Gram-positive bacterium; angiogenesis; carbohydrate derivative transport; cell adhesion; endocytosis; receptor-mediated endocytosis; hyaluronan catabolic process
Cellular component: cytoplasm; cytosol; plasma membrane; endocytic vesicle membrane; external side of plasma membrane
Genetic constraint (gnomAD): Loss-of-function variants: 274 observed, 334.28 expected, observed/expected ratio (o/e) 0.82, 90% interval 0.74 to 0.91. The upper end of that interval is the gene's LOEUF score, 0.91, which puts it in group 3 of 6, group 1 being the genes least tolerant of losing a copy. Missense variants: 3,078 observed, 3,269 expected, observed/expected ratio (o/e) 0.94, 90% interval 0.91 to 0.97. Synonymous variants: 1,176 observed, 1,215.2 expected, observed/expected ratio (o/e) 0.97, 90% interval 0.92 to 1.01.
Homologues: Orthologues: chimpanzee STAB2 (99% identical), macaque STAB2 (95% identical), rabbit STAB2 (82% identical), dog STAB2 (80% identical), rat Stab2 (79% identical), mouse Stab2 (78% identical), guinea pig STAB2 (65% identical), tropical clawed frog stab2 (60% identical), zebrafish stab2 (48% identical). Paralogues in human: STAB1 (40% identical), TNFAIP6 (3% identical).
Diseases named in the same sentence as STAB2 in open-access papers:
STAB2 is named in the same sentence as 33 diseases in open-access papers, as found by Europe PMC text mining. Sharing a sentence is not in itself a finding about the gene and the disease. The quoted sentences say what the papers report.
atherosclerosis (8 papers, 2015 to 2024). A disease characterized by the build-up of fatty material and calcium deposition in the arterial wall resulting in partial or complete occlusion of the arterial lumen. "DBA/2J allele of Stab2 locus (Stab2DBA) was linked to the elevation of plasma HA concentration, as well as the protection from atherosclerosis in the F2 population of DBA/2J-Apoe−/− × 129S6-Apoe−/− intercross." (PMID 31912264, 2020). "While targeted inhibition of Stab1 or Stab2 might be beneficial in the context of atherosclerosis prevention, double deficiency leads to premature organ failure likely due to multi‐ligand depositions caused by deficient hepatic scavenging." (PMID 37357460, 2023). "In this study, we demonstrated that Aath5 affects atherosclerosis by establishing an Apoe−/− line on a 129S6 background that are homozygous for Aath5 of DBA/2J allele, and further examined the role of Stab2 in atherosclerosis by generating Stab2−/−Apoe−/− mice on a C57BL/6J background." (PMID 35360009, 2022). "Similarly, Scavenger Receptors Stabilin-1 and Stabilin-2 were associated with atherosclerosis, and inhibition of Stabilin-1/Stabilin-2 can significantly reduce Erg1 expression in mononuclear macrophages, thus reducing the progression of atherosclerosis." (PMID 37123263, 2023). "Finally, although the major ligand of STAB2, HA, is implicated in atherosclerosis, HA could be protective or harmful depending on the context." (PMID 35360009, 2022). "Stab1 and Stab2 have been shown to influence fibrosis in liver and kidneys and to modulate inflammation in atherosclerosis." (PMID 38946049, 2024). "Stab1 and Stab2 single inhibition mediates beneficial effects in atherosclerosis development, anti‐Stab1 inhibition is in clinical trials in immune‐oncology." (PMID 37357460, 2023). "Stab2 is reported to be expressed in the atherosclerotic plaques in humans, although the role of Stab2 in atherosclerosis is unclear." (PMID 35360009, 2022). "Another ligand of STAB2, von Willebrand Factor (vWF), mediates vascular inflammation and enhances atherosclerosis by stimulating the adhesion of platelets onto the vessels." (PMID 35360009, 2022). "Quantitative trait loci analyses in mice suggested candidate genes, including Mertk and Stab2, although how each gene affects the location-specific atherosclerosis needs further elucidation." (PMID 33260687, 2020). "Our best candidate genes, Hdc, Mertk and Cd93 for Aath4 and Stab2 for Aath5, all play pivotal roles in early processes of atherosclerosis by regulating leukocyte recruitment, macrophage activation, and inflammation." (PMID 25689165, 2015). "Our study using the backcrossed mice and the gene-edited mice demonstrated that Stab2, a candidate of Aath5, is likely a modifier of atherosclerosis, but the effect can be easily flipped depending on the genotypes of other loci with greater influential effects." (PMID 35360009, 2022). "Since platelet-endothelial interaction is a contributing factor in atherosclerosis, STAB2 could affect lesion development via vWF/FVIII." (PMID 35360009, 2022). "To test whether Stab2 is a modifier of atherosclerosis, we generated Stab2−/−Apoe−/− mice on C57BL/6 background." (PMID 35360009, 2022). "In summary, our results indicate that Stab2 is likely a modifier gene of atherosclerosis." (PMID 35360009, 2022). "Despite the support from these observations, whether and how Stab2 relates to the location-specific atherosclerosis remains to be elucidated." (PMID 33260687, 2020). "The effect of Stab2 inhibition on atherosclerosis is currently under investigation." (PMID 31912264, 2020). "Knockout mice lacking Stab2 exhibit no specific phenotype except that they have elevated circulating hyaluronan, though the effects of the lack of Stab2 on atherosclerosis has not been evaluated." (PMID 25689165, 2015). "In the current work we explored several possible mechanisms by which the lack of Stab2 could lead to the protection against atherosclerosis." (PMID 35360009, 2022).
atherosclerosis (continued). "Since anti-Stab1 therapies are already in Phase I/II clinical trials and Stab1/Stab2 inhibition has therapeutic promise in atherosclerosis, non-homeostatic disease models of genetic Stabilin deficiency might allow predicting side-effects of anti-Stabilin antibodies." (PMID 37446152, 2023). "However, there is no investigation directly evaluating that Stab2 is involved in atherosclerosis." (PMID 35360009, 2022).
liver fibrosis (5 papers, 2021 to 2024). "Our findings here give further insights into the scavenging of fasciclin domain proteins TGFBi and POSTN, which are heavily implicated in liver fibrosis and hepatocellular carcinoma, through Stab1 and Stab2 and in liver fibrosis models." (PMID 37446152, 2023). "To conclude, we show how liver fibrosis in preclinical models differentially correlates with TGFBi and POSTN levels in response to deficiency for Stab1 or Stab2, bearing consequences for potential anti-Stabilin therapies." (PMID 37446152, 2023). "We showed that impaired clearance of GDF-15 in STAB-1–/–STAB-2–/– mice leads to severe glomerular fibrosis and mild perisinusoidal hepatic fibrosis." (PMID 34975851, 2021). "In contrast, deletion of both, Stab1 and Stab2, resulted in premature mortality with severe glomerular kidney fibrosis and only mild liver fibrosis and dysfunction." (PMID 33745018, 2021). "Stabilin-2, which has been found to reduce the concentration of low-density lipoproteins, the main molecule responsible for atherosclerosis and indirectly liver fibrosis, has been identified as a promising biomarker for liver fibrosis and a potential therapeutic target." (PMID 39457542, 2024). "While Stab1-deficient (Stab1−/−) mice were shown to exhibit higher liver fibrosis levels upon challenges, fibrosis susceptibility has not been studied in Stab2-deficient (Stab2−/−) mice." (PMID 37446152, 2023). "Similar to sinusoidal capillarization in liver fibrosis and cirrhosis, transdifferentiation of the sinusoidal vasculature is observed in human and murine HCC with loss of LSEC markers STAB1, STAB2, LYVE-1, CD32b, and GPR182 and induction of the continuous EC marker CD31." (PMID 33745018, 2021).
hepatocellular carcinoma (4 papers, 2020 to 2025). A malignant tumor that arises from hepatocytes. "In hepatocellular carcinoma, endothelial transdifferentiation is a major pathogenic event and stabilin-2 could accelerate endothelial-tumor cell adhesive interactions and microvascular invasion." (PMID 34227915, 2021). "In light of the hypothesis that Stabilin-2 may aid in the retention of metastatic cells, a study focused on the remodeling of endothelium in hepatocellular carcinoma (HCC) revealed that the loss of Stabilin-2 expression increased survival of the patients that were sampled." (PMID 32429122, 2020). "During hepatocellular carcinoma (HCC) progression in humans, LSECs lose the expression of their markers, including lymphatic vessel endothelial hyaluronan receptor-1 (LYVE-1), CD32b, stabilin-1, and stabilin-2." (PMID 40595432, 2025).
melanoma (3 papers, 2015 to 2023). A malignant, usually aggressive tumor composed of atypical, neoplastic melanocytes. "Blocking Stab2 function prevents melanoma metastasis by elevating circulating hyaluronic acid levels." (PMID 36059952, 2022). "Increased serum levels of LMW-HA, created by blocking the HA receptor for endocytosis (HARE/Stab2) found in sinusoidal endothelium in the liver, bone marrow, and lymph nodes, prevented B16F10 melanoma cells from binding to endothelial cells and producing lung foci in tail-vein injected mice." (PMID 26539408, 2015).
prostate carcinoma (3 papers, 2015 to 2025). A carcinoma that arises from epithelial cells of the prostate gland. "The study found that the mutant T allele in HMMR-rs299295 and the G allele in STAB2-rs2271637 are associated with an increased risk of prostate neoplasm, including benign prostatic hyperplasia and prostate cancer (p < 0.001)." (PMID 40567905, 2025). "It is reported that expression of STAB2 in prostate cancer is correlated with patients’ advanced stage." (PMID 34227915, 2021). "STAB2 has been found to have the role to aid the diagnosis of malignant disease in prostate cancer patients." (PMID 34227915, 2021). "Our study found a significant association between the mutant T allele in HMMR-rs299295 (A485V) and the mutant G allele in STAB2-rs2271637 (L2401V) variants and an increased risk of prostate neoplasm, including both groups (BPH, prostate cancer) compared to control men." (PMID 40567905, 2025).
prostate tumor (3 papers, 2015 to 2025). "The study aims to investigate 2 gene variants, HMMR-rs299295 and STAB2-rs2271637, with the risk of prostate neoplasms based on a case-control and in silico study in the Mazandaran province (Iran) population." (PMID 40567905, 2025). "The study aims to investigate the relationship between the HMMR-rs299295 (C>T/ A485V) and STAB2-rs2271637 (C>G/ L2401V) gene variants and the risk of prostate neoplasms in the Mazandaran population, North of Iran." (PMID 40567905, 2025). "The mutant alleles of T in HMMR-rs299295 and the G in STAB2-rs2271637 may disrupt protein structures and probably contribute to prostate neoplasm progression." (PMID 40567905, 2025). "Although the provided references do not directly address the association of prostate neoplasm with the ABCC5, HYAL2, and SLC9A1 proteins, it appears that the HMMR-rs299295 and STAB2-rs2271637 variants may play a role in the growth, proliferation, and metastasis of prostate neoplasm." (PMID 40567905, 2025).
liver cancer (2 papers, 2021 to 2022). An epithelial or non-epithelial malignant neoplasm that arises from the liver. "Thereby, loss of Stabilin-2 expression showed increased survival in patients with liver cancer." (PMID 34227915, 2021).
liver disease (2 papers, 2019 to 2023). "A very high correlation of TGFBi to overall fibrotic burden was observed in the liver, indicating that loss of Stab1 or Stab2 alone does not seem to impede scavenging of POSTN or TGFBi, even in liver disease models in these mice." (PMID 37446152, 2023).
Nephropathy (2 papers, 2018 to 2022). A nonspecific term referring to disease or damage of the kidneys. "Under physiological conditions, only a simultaneous deletion of Stab1 together with its close homolog Stab2 results in glomelurofibrotic nephropathy possibly by impairing the clearance of profibrotic cytokine GDF-15 in the liver." (PMID 30349531, 2018).
osteosarcoma (2 papers, 2020 to 2023). A usually aggressive malignant bone-forming mesenchymal neoplasm, predominantly affecting adolescents and young adults. "Comprehensively, we considered that the STAB2 might serve as the key target in treating osteosarcoma." (PMID 37870753, 2023). "Immunohistochemical stains were positive for stabilin-2 and negative for cytokeratin, which confirmed the diagnosis of osteosarcoma." (PMID 32312303, 2020).
venous thromboembolic disease (2 papers, 2022 to 2024). "The GWAS Catalog lists significant association of SNPs in or near the STAB2 gene with circulating vWF and FVIII levels, and recent human and mouse studies indicate Stab2 is involved in venous thromboembolism." (PMID 35360009, 2022).
anemia (1 paper, 2021). A reduction in the number of red blood cells, the amount of hemoglobin, and/or the volume of packed red blood cells. "Mice with stabilized β-catenin in BM-SEC (Ctnnb1OE-SEC) generated by using a BM-SEC-restricted Cre mouse line (Stab2-iCreF3) develop fatal anemia." (PMID 34845225, 2021).
breast carcinoma (1 paper, 2021). "In this review, we focus upon the biology of CD44 and RHAMM because—unlike LYVE1, STAB2/HARE, and LAYN—these receptors have been studied in detail in the context of cutaneous wound repair and breast cancer and because they are well characterized to directly bind to HA." (PMID 34827550, 2021).
COVID-19 (1 paper, 2023). A disease caused by infection with severe acute respiratory syndrome coronavirus 2. "All three proteins enriched in lymphoid organs, i.e., STAB2, Leukocyte Immunoglobulin-Like Receptor B1 (LILRB1), and CR2, had decreased serum levels in COVID-19 patients." (PMID 37739942, 2023).
endothelial dysfunction (1 paper, 2025). In vascular diseases, endothelial dysfunction is a systemic pathological state of the endothelium (the inner lining of blood vessels) and can be broadly defined as an imbalance between vasodilating and vasoconstricting substances produced by (or acting on) the endothelium. "After alcohol cessation Lyve1 and Stab2 expression returned to control levels, but in contrast, Icam1, Vcam1, and Cd34 stayed elevated or further increased suggesting that endothelial dysfunction persists after alcohol cessation." (PMID 40288442, 2025).
Hepatitis (1 paper, 2021). Inflammation of the liver. "Plasma GAGs are removed from circulation by clearance receptors present on liver sinusoidal ECs such as stabilin-2, and injury or infection of the liver is associated with increases in circulating GAGs as in the case of hepatitis." (PMID 34314391, 2021).
lymph node metastasis (1 paper, 2021). "In conclusion, high expression of Stabilin-2 has significant correlations with lymph node metastasis and impaired survival in non-small cell lung cancer (NSCLC)." (PMID 34227915, 2021).
mastitis (1 paper, 2018). Inflammation of breast tissue during lactation or postpartum due to an obstructed duct or infection. "The SNP rs109785134 on BTA5, an intron variant in significant association with susceptibility to mastitis in parity 2, is located within a protein coding gene STAB2 (stabilin-2 precursor)." (PMID 29755506, 2018). "Genes involved in lymphocyte developments (e.g., MAST3 and STAB2) and genes involved in macrophage recruitment and regulation of inflammations (PDGFD and PTX3) were suggested as possible causal genes for susceptibility to – and recoverability from mastitis, respectively." (PMID 29755506, 2018).
non-small cell lung carcinoma (1 paper, 2021). A group of at least three distinct histological types of lung cancer, including non-small cell squamous cell carcinoma, adenocarcinoma, and large cell carcinoma. "However, further investigation on the mechanism of Stabilin-2 regulating the progression of non-small cell lung cancer (NSCLC) is still needed." (PMID 34227915, 2021). "Stabilin-2 can be a potential therapeutic target for non-small-cell lung cancer." (PMID 34227915, 2021). "And this result just suggested that Stabilin-2 might act as an oncogene in stimulating the progression of non-small-cell lung cancer." (PMID 34227915, 2021).
psoriasis (1 paper, 2024). An autoimmune condition characterized by red, well-delineated plaques with silvery scales that are usually on the extensor surfaces and scalp. "Psoriasis‐like changes are reduced in Stab2‐deficient mice with increased TGFBi levels compared to Stab1‐deficient mice, while scleroderma‐like effects show no differential impact." (PMID 38946049, 2024). "Whether monoclonal‐antibody‐mediated inhibition of Stab2 may be useful as therapy for psoriasis needs to be evaluated in future studies." (PMID 38946049, 2024).
pulmonary arterial hypertension (1 paper, 2019). Pulmonary arterial hypertension (PAH) is a group of diseases characterized by mean pulmonary artery pressure >20 mmHg and elevated pulmonary arterial resistance leading to right heart failure. "Differential methylation of STAB2 was associated with pathophysiology of the cardiovascular system including pulmonary arterial hypertension." (PMID 31281827, 2019).
stomach cancers (1 paper, 2021). "In solid tumors such as tongue, lung, and stomach cancers, Stabilin-2 tended to be expressed in the sinusoidal endothelial cell within the metastatic lymph nodes." (PMID 34227915, 2021).